CXCR4 (C-X-C motif chemokine receptor 4)
Diseases named in the same sentence as CXCR4 in open-access papers (continued):
Sharing a sentence is not in itself a finding about the gene and the disease.
Stroke (continued). "Recently, several studies reported that systemic treatment with AMD3100, a highly selective CXCR4 antagonist, significantly improved the functional outcome following experimental stroke through attenuating the inflammatory response and microglial activation." (PMID 28785202, 2017). "In the stroke model, stem cells are chemo-attracted to the site of the infarction by cytokines with one molecular pathway being CXCR4/CXCL-12 (SDF-1) signaling." (PMID 27013982, 2016). "Hampered CXCL12/CXCR4 signaling by AMD3100 downregulates the migration of neuroblasts at the site of ischemic injury 4 weeks after stroke." (PMID 25881123, 2015). "Two independent studies demonstrated that blockade of the CXCL12/CXCR4 axis improved the functional outcome after stroke by attenuating post-ischemic inflammation." (PMID 25374510, 2014). "In the present study, the SDF-1α levels increased, but the CD105+/CXCR4+/AV− microparticles decreased with time after the onset of stroke." (PMID 22615882, 2012). "Deeper clinical research could confirm the effects of rTMS on PSCI, white matter integrity and the SDF‐1α/CXCR4 axis after stroke." (PMID 41355332, 2025). "Hence, it is theoretically possible that rTMS regulates structural plasticity and promotes behavioral recovery by increasing the expression of SDF‐1α/CXCR4 axis components in ischemic brain tissues after stroke." (PMID 41355332, 2025). "Therefore, high CXCR4 expression in neutrophils underscores the importance of aged neutrophils in the pathogenesis of CE stroke." (PMID 41329022, 2025). "Intravenous injection of EXO‐PD‐L1‐HGF could target stromal cell‐derived factor‐1α (SDF‐1α+) cells over the peri‐infarcted area of the ischemic brain through CXCR4 upregulation and accumulation in neuroglial cells post‐stroke." (PMID 39049677, 2024). "The effects of SDF‐1α/CXCR4 are time‐sensitive, as delayed treatment several days after initial stroke appears to optimize functional improvements, suggesting early manipulation may interfere with necessary inflammatory processes." (PMID 38379112, 2024). "However, our studies validating the involvement of CD13 and CXCL12/CXCR4 in human stroke patients, that were older and both sexes (mean age − 61–92 years) suggests that this is also relevant to clinical stroke." (PMID 37817190, 2023). "Moreover, by cross-validation with other CE stroke-related datasets, CXCR4 was identified as a pathogenetic marker for all types of strokes." (PMID 37305740, 2023). "CXCL12 was reported to be involved in the migration of CXCR4+ monocytes towards stroke." (PMID 36631780, 2023). "Glyburide, an antistroke agent, was incorporated into the PLGA nanoparticle cores, followed by coating with the NSC membrane engineered with CXCR4; this strategy was used for the stroke-targeting delivery and stroke treatment due to the interaction of SDF-1-CXCR4 axis." (PMID 37111742, 2023). "However, there is limited data on the aspect of how the CXCR4/CXCR7/CXCL12 axis modulates neuronal function following stroke." (PMID 35401118, 2022). "Also, blocking migration towards the lesion by Cxcr4 deletion specifically in NKs and ILC1s protects motor-behavior after stroke ischemic induction." (PMID 35185929, 2022). "More specifically, C-X-C motif ligand 12 (CXCL12, also known as SDF-1α) expression increases in the infarct area after AMI or stroke, and then triggers the migration of CXCR4+ inflammatory cells and CXCR4+ endothelial progenitor cells (EPCs) to the lesioned sites." (PMID 36233031, 2022). "However, we have observed that CXCR4+ NK cells protect motor behavioral functions in the photothrombotic stroke model by using anti-NK1.1 mediated depletion." (PMID 35185929, 2022). "Indeed, Cxcr4 gene ablation reduced monocyte infiltration and response gene expression in experimental stroke in mice." (PMID 34054860, 2021).
Stroke (continued). "It was shown that preconditioning MSCs with stroke patients' sera enhanced the METR/HIF‐1/CXCR4 pathway and increased the migratory potential of MSCs, which translated into improved recovery in a transient middle cerebral artery occlusion (tMCAO) stroke model in rats." (PMID 32573961, 2020). "Physical exercise regulates neural stem cells via CXCR4 in rats after stroke." (PMID 31595394, 2020). "Moreover, the ubiquitously active CAG promoter in R26CAG-LSL-tdT enabled MDMs to be traced, despite their downregulation of CXCR4 in the CNS during stroke." (PMID 33363542, 2020). "Another well-studied chemokine axis in stroke involves CXCR4 and CXCL12." (PMID 31544811, 2019). "LRRK2, CALM1, CXCR4, TLR4, CTNNB1, and CXCR2 may be implicated in AF and the hub-genes of CD19, FGF9, SOX9, GNGT1, and NOG may be associated with stroke." (PMID 30760287, 2019). "Importantly, by sustained blocking of the SDF-1α/CXCR4 pathway, linagliptin-mediated effects on functional and histological outcomes after stroke were diminished." (PMID 29776406, 2018). "Moreover, the study was terminated at Day 3 after stroke to avoid the potential global side effects of chronic CXCR4 blocking." (PMID 29776406, 2018). "In the present study, we investigated whether protective effects of linagliptin after stroke are mediated via SDF-1α by blocking CXCR4 with the selective CXCR4 antagonist AMD3100." (PMID 29776406, 2018). "We showed that linagliptin improves functional stroke outcome in a SDF-1α/CXCR4-dependent manner." (PMID 29776406, 2018). "The primary objective of this study was to determine whether the improved outcome after stroke following gliptin treatment is SDF-1α/CXCR4-dependent." (PMID 29776406, 2018). "We aimed to determine whether the gliptin linagliptin improves stroke outcome via the SDF-1α/CXCR4 pathway, and identify additional effectors behind the efficacy." (PMID 29776406, 2018). "One can speculate that SDF-1/CXCR4/CXCR7 signaling pathways may become new therapeutic targets since they hold the possibility of promoting a functional recovery after a stroke." (PMID 29123467, 2017). "SDF-1 expression was higher in the ischemic boundary zone after stroke, which may facilitate the migration of CXCR4-positive stem cells." (PMID 28499457, 2017). "Results support the idea that specific CXCR4 antagonism might be exploited in future approaches to improve rehabilitative treatment in stroke patients." (PMID 25881123, 2015). "Thus, antagonism of CXCR4 reduces the release of FKN after stroke, which confirms earlier published data." (PMID 25881123, 2015). "This could be useful in order to allow the CXCR4-dependend migration of cells important for brain recovery after stroke such as mesenchymal stem cells." (PMID 25374510, 2014). "Additionally, we performed CXCR4 IHC in stroke patients in whom we discovered an upregulation of CXCR4 in the glial cells and especially astroglial cells." (PMID 23832647, 2013). "Furthermore, CXCR4-regulated microglia were recruited to sites of brain injury in a zebrafish model and CXCR4 was expressed in human stroke patients, suggesting a conserved role in damage responses to various types of brain injuries." (PMID 23832647, 2013). "The chemokine receptors CCR2, CCR5, CXCR2, CXCR3, CXCR4 and CX3CR1 are constitutively expressed in the human brain, and their expression is enhanced under pathological conditions, including stroke and neurodegenerative diseases like HIV-associated dementia (HAD) and Alzheimer’s disease (AD)." (PMID 23210607, 2012). "CXCR4 was upregulated 3 d after stroke in both the core and PI area." (PMID 23284893, 2012). "First, a different peak time between SDF-1α and CD105+/CXCR4+/AV− microparticles after stroke may prevent a putative relationship between serum chemokine and its receptor on microparticles." (PMID 22615882, 2012).
Stroke (continued). "After stroke, many inflammation cytokines and chemokines were released into peripheral blood including vascular cell adhesion molecule 1, p-selectin, CXCR4 and SDF-1, which promote the adhesion of MSCs to the endothelium or induce the migration of MSCs to the ischemic tissue in the brain." (PMID 21733181, 2011). "Moreover, to ensure that the CMCNPs could target the stroke area, they applied a viral transformation to over-express CXCR4 on the NSCs while culturing them." (PMID 36839943, 2023). "Indeed, CXCR4+ NK cells were shown to extravasate from the blood in patients specifically during the remission phase of multiple sclerosis, and were also observed in stroke regions in patients." (PMID 36631780, 2023). "In the present study, we hypothesized that exosomes derived from BMSCs could effectively regulate cell survival, promote angiogenesis, protect nerve cells, and improve stroke outcome in the acute stage of stroke, through upregulating CXCR4 in exosomes of BMSCs." (PMID 33381162, 2020). "CXCR4 antagonists may be useful in treating both types of stroke in patients." (PMID 32992950, 2020). "CXCL12 and CXCR4 are constitutively expressed and widely detected in the CNS, especially in microglia, and have been shown to play important roles in the physiology of the brain and in pathological conditions, such as stroke, multiple sclerosis (MS), and some neurodegenerative diseases." (PMID 31831012, 2019). "The linagliptin effects via SDF-1α/CXCR4 to reduce the brain injury after stroke could also be mediated by the regulation of neovascularization through endothelial progenitor cells (EPCs) since gliptins increase ischemic angiogenesis by preserving EPCs function." (PMID 29776406, 2018). "rTMS reduced cerebral infarct severity, ameliorated white matter injury and promoted behavioral recovery after stroke in addition to increasing SDF‐1α and CXCR4 expression." (PMID 41355332, 2025). "EPCs exist in the bone marrow stem cell niche and are mobilised in response to chemokines and growth factors known to be upregulated in stroke including Stromal cell-derived factor 1 (SDF-1) and its cellular receptor C-X-C chemokine receptor type 4 (CXCR4)." (PMID 40742699, 2025). "Stimulation of Treg cells with stroke brain lysates increased C-X-C motif chemokine receptor 4 (CXCR4) expression, indicating a potential role for the CXCL12-CXCR4 axis in recruiting Treg cells." (PMID 40313089, 2025). "After a stroke, large quantities of SDF-1α are released in the ischemic area, which has a robust recruitment effect on SCs expressing CXCR4, and achieves the target outcome." (PMID 38357525, 2024). "Therefore, targeting the inhibition of CXCR4 could prevent the occurrence of stroke." (PMID 37305740, 2023). "Flow cytometry was performed on days 3 and 7 post-stroke to quantify infiltrated monocytes and neutrophils and CXCL12/CXCR4 signaling." (PMID 37817190, 2023). "Aside from the benefits regarding our understanding of post-stroke migration to lesions, the implications of LRP1 regulation of CXCR4 are broad, as CXCR4 plays a vital role in multiple neurogenic and stem cell processes." (PMID 37186298, 2023). "Through intercellular receptor transactivation between CXCR4 and IGF1R signaling pathways, implantation of IGF1R+ MSCs showed significant improvement in neurological function in a stroke model." (PMID 36017096, 2022). "Accordingly, CXCR4/SDF-1 promotes angiogenesis, improves cerebral neurogenesis, and facilitates cerebral vascular regrowth after a stroke." (PMID 31658727, 2019). "We demonstrated before that HP increased BMSC homing to the stroke site was mediated by the mechanism involving FAK and CXCR4 upregulation." (PMID 29649974, 2018). "HP of BMSCs increases CXCR4 expression, suggesting an important role of the SDF-1α/CXCR4 axis in HP-mediated homing of HP-BMSCs to the stroke region." (PMID 29649974, 2018).
Stroke (continued). "Our results suggest that, at least when it comes to post-stroke treatment, the activation of the SDF-1α/CXCR4 pathway promotes beneficial effects." (PMID 29776406, 2018). "There is now convincing data indicating that SDF-1/CXCR4/CXCR7 can promote neurogenesis and angiogenesis, two interdependent processes required for recovery after a stroke." (PMID 29123467, 2017). "SDF-1 is upregulated in the ischemic penumbral region after stroke, and the interaction between SDF-1 and CXCR4 triggers BMSCs migration toward the injured area." (PMID 28499457, 2017). "The level of SDF-1α increased with time after stroke onset (r = 0.248, p = 0.011), whereas the levels of CD105+/CXCR4+/AV− microparticles decreased with time after stroke onset (r = −0.204, p = 0.036)." (PMID 22615882, 2012). "Furthermore, these findings suggest the potential for neutrophil‐targeted interventions, such as DNase or CXCR4 antagonists like AMD3100, to reduce thrombus formation and improve clinical outcomes specifically in CE stroke." (PMID 41329022, 2025). "In addition to preserving tight junctions, SDF‐1α/CXCR4 signaling also stimulates angiogenesis and new blood vessel formation via VEGF/eNOS pathways to revascularize the neurovascular unit after stroke." (PMID 38379112, 2024). "In addition, CXCR4, the CXCL12 receptor, was expressed by lineage traced cells arising from the SVZ after stroke." (PMID 37816732, 2023). "Moreover, in certain pathological states, like stroke and diabetes, blocking the CXCL12/CXCR4 axis by AMD3100 treatment led to elevated populations of activated macrophages in the ischemic cortex or skin wounds." (PMID 35615089, 2022). "CXCR4 antagonists CX549 or AMD3100 reduced microglia activation and T cell infiltration in the ischemic hemisphere and facilitated functional recovery in stroke animals." (PMID 32992950, 2020). "It suggests associations of the CD45–CD34 + CD133+ cells with the neurological status of stroke patients, and some activity of the CD45–CD34 + CD133+, the CD45–CD34 + CXCR4+, and the CD45–CD34 + CXCR7+ progenitor/stem cells in the process of arterial remodeling." (PMID 29744773, 2018). "Blockade of the CXCR4 or CXCR7 could disrupt the migration of NSCs, leading to a failure of the newborn neurons to migrate to the ischemic tissue in animal models of stroke." (PMID 29896417, 2018). "The role of SDF-1α in cerebral ischemic injury is complex since some studies have shown positive effects of SDF-1α in the acute phase after stroke whereas other studies have demonstrated positive effects by blocking the SDF-1α/CXCR4 pathway in the recovery phase after stroke." (PMID 29776406, 2018). "In rat stroke model, animals receiving IGF1R+ hDSCs transplantation, interaction between IGF1R and CXCR4 was demonstrated to promote neuroplasticity, therefore improving neurological function through increasing glucose metabolic activity, enhancing angiogenesis and anti-inflammatiory effects." (PMID 27586516, 2016). "The levels of CD105+/CXCR4+/AV− microparticles were also increased in patients with severe disability (r = 0.192, p = 0.046 for NIHSS score on admission), but were decreased with time after stroke onset (r = −0.204, p = 0.036)." (PMID 22615882, 2012). "Although circulating EPCs has been reported in patients with ischemic insults, no studies have investigated circulating CD105+ or CXCR4+ cells or microparticles in stroke patients to date." (PMID 22615882, 2012). "Thus, combination treatment of stroke upregulates the SDF1/CXCR4 axis and enhances BMSC migration into the ischemic brain, amplifies arteriogenesis and angiogenesis, and improves functional outcome after stroke." (PMID 21804783, 2010). "Indeed, at P2 we noted that CXCR4+ NK cells were significantly increased within the blood of mice which received photothrombotic stroke, while the total NK cell population did not change significantly." (PMID 36631780, 2023).
Stroke (continued). "After an ischemic stroke, it was discovered that the SDF-1 receptor, CXCR4, was expressed in neural progenitors and stroke-generated neuroblasts and that the expression of SDF-1 was increased in reactive astrocytes and activated microglia in the injured area and stroke hemisphere." (PMID 37242489, 2023). "Consistently, the CXCR4 antagonists AMD3100 and CX549 were both efficient to mobilize bone marrow hematopoietic stem cells (HSCs), improving behavioral performances, reducing brain infarction, and suppressing the expression of inflammatory markers in stroke brain." (PMID 37305740, 2023). "As for CXCR2, anti-CXCR4 Nbs have been developed, but have not yet been tested in stroke." (PMID 31544811, 2019). "Interestingly, our data also showed that CXCR7, but not CXCR4, was significantly increased in the peri-infarcted regions in human stroke brain." (PMID 29896417, 2018). "We also hypothesized that cross-talk between IGF1R and CXCR4 signaling pathways in IGF1R+ hDSC might exert autocrine/paracrine induction of an additive survival signal to enhance neurite regeneration and neuroplasticity in hDSC-transplanted stroke model." (PMID 27586516, 2016). "The effects of linagliptin to reduce the injury after stroke could involve the neuroprotective, non-neurogenic rapid effects of neural progenitor cells (NPCs) since CXCR4 inhibition in NPCs leads to failure of newborn neurons to localize to the ischemic brain tissue." (PMID 29776406, 2018). "Microbiota-colonized Ex-GF stroke mice showed a slight reduction in the percentage of CD62L+ immature neutrophils in the blood (< 1%) and spleen but not in BM and a higher frequency of CXCR4+ activated neutrophils in the blood and spleen, but not in BM." (PMID 40410847, 2025).